DSCC1 (DNA replication and sister chromatid cohesion 1)
Description:
Loads PCNA onto primed templates regulating velocity, spacing and restart activity of replication forks. May couple DNA replication to sister chromatid cohesion through regulation of the acetylation of the cohesin subunit SMC3.
Synonyms: DCC1; hDCC1; MGC5528
Tractability: PROTAC: ubiquitination databases record sites on it.
Gene: Protein-coding gene on chromosome 8 (119,833,944 to 119,855,987, reverse strand). Ensembl gene ENSG00000136982.
Subcellular location: Nucleus
Subcellular location (Human Protein Atlas): Nucleoplasm
Pathways (Reactome):
Cell Cycle: Polymerase switching on the C-strand of the telomere
Gene Ontology:
Molecular function: DNA clamp loader activity; protein binding; single-stranded DNA helicase activity
Biological process: maintenance of mitotic sister chromatid cohesion; positive regulation of DNA-directed DNA polymerase activity; post-translational protein acetylation; regulation of DNA replication; DNA replication; mitotic sister chromatid cohesion
Cellular component: chromatin; chromosome, centromeric region; Ctf18 RFC-like complex; nucleoplasm; nucleus
Genetic constraint (gnomAD): Loss-of-function variants: 23 observed, 38.49 expected, observed/expected ratio (o/e) 0.6, 90% interval 0.43 to 0.85. The upper end of that interval is the gene's LOEUF score, 0.85, which puts it in group 3 of 6, group 1 being the genes least tolerant of losing a copy. Missense variants: 370 observed, 400.05 expected, observed/expected ratio (o/e) 0.92, 90% interval 0.85 to 1.01. Synonymous variants: 136 observed, 141.45 expected, observed/expected ratio (o/e) 0.96, 90% interval 0.84 to 1.11.
Homologues: Orthologues: chimpanzee DSCC1 (99% identical), macaque DSCC1 (98% identical), pig DSCC1 (92% identical), rabbit DSCC1 (92% identical), rat Dscc1 (88% identical), mouse Dscc1 (85% identical), dog DSCC1 (72% identical), tropical clawed frog dscc1 (71% identical), zebrafish dscc1 (67% identical), Drosophila melanogaster CG11788 (29% identical), Caenorhabditis elegans dscc-1 (25% identical).
Diseases named in the same sentence as DSCC1 in open-access papers:
DSCC1 is named in the same sentence as 21 diseases in open-access papers, as found by Europe PMC text mining. Sharing a sentence is not in itself a finding about the gene and the disease. The quoted sentences say what the papers report.
colorectal cancer (10 papers, 2014 to 2024). A primary or metastatic malignant neoplasm that affects the colon or rectum. "DSCC1 is implicated in sister chromatid cohesion and DNA replication, and its elevated expression decreases apoptosis in colorectal cancer cells." (PMID 30138346, 2018). "DSCC1 is associated with the development of colorectal cancer through inhibition of apoptosis, but this gene may be responsible for the inhibition of apoptosis in BRCA." (PMID 31311202, 2019). "DSCC1's regulation involves various transcription factors; for instance, in colorectal cancer, the upregulated transcription factor E2F1 possesses binding sites within the DSCC1 promoter, resulting in DSCC1 upregulation and impacting colorectal cancer cells." (PMID 39309429, 2024). "Previous investigations have shown that colorectal cancer, lung adenocarcinoma, and hepatocellular carcinoma cells display higher levels of DSCC1." (PMID 39768811, 2024). "DSCC1 overexpression is reported to contribute to the growth of tumor cells in colorectal cancer, hepatocellular carcinoma, and lung cancer." (PMID 39768811, 2024). "DSCC1, involved in DNA replication and sister chromatid cohesion, is actually frequently upregulated in colorectal cancer cells, where it is shown here to be even more upregulated in GCA compared to colorectal adenocarcinoma." (PMID 34804955, 2021). "DSCC1 is involved in the cancer progression and its suppression may be a useful option for the treatment of multiple cancer, including colorectal cancer, breast cancer and hepatocellular carcinoma." (PMID 37742009, 2023). "RNAi-mediated reduction of E2F1 reduced expression of DSCC1 in colorectal cancer cells." (PMID 24465681, 2014). "We reveal that E2F-dependent expression of DSCC1 confers anti-apoptotic properties in colorectal cancer cells, and that its suppression may be a useful option for the treatment of colorectal cancer." (PMID 24465681, 2014). "DSCC1 is more upregulated in GCA than colorectal adenocarcinoma; KCNQ1OT1 and MXRA5 are downregulated in GCA, compared to other colorectal cancers." (PMID 40729214, 2024). "Among the genes deregulated in colorectal tumors, expression of DNA replication and sister chromatid cohesion 1 (DSCC1) was increased more than two-fold in 5 of 7 colorectal cancers compared with corresponding non-cancerous colon mucosa." (PMID 24465681, 2014).
breast carcinoma (7 papers, 2007 to 2024). "Recently, overexpression of DSCC1 (DNA replication and sister chromatid cohesion 1) was found to increase proliferation, invasion and migration of breast carcinoma cells, as well as its knockdown showed opposite outcomes." (PMID 35167614, 2022). "In the present study, DSCC1 is significantly up-expressed in each breast cancer subtype except luminal A, compared with normal samples." (PMID 33313822, 2021). "Materials and Methods: The association of clinicopathological features and patient outcomes with DSCC1 expression at the mRNA level was assessed using the Molecular Taxonomy Breast Cancer International Consortium (METABRIC; n = 1980) and The Cancer Genome Atlas (TCGA; n = 854) cohorts." (PMID 39768811, 2024).
gastric cancer (5 papers, 2019 to 2024). A primary or metastatic malignant neoplasm involving the stomach. "In the Gastric cancer-KO group, the mRNA expression levels of DSCC1 and GINS1 were significantly lower than in the “Gastric cancer” group (P < 0.01)." (PMID 38301047, 2024). "A heatmap of core gene expression in Gastric cancer survival data indicated that the core genes, DSCC1 and GINS1, acted as protective factors." (PMID 38301047, 2024). "In the Gastric cancer-OE group, the mRNA expression levels of DSCC1 and GINS1 were significantly higher than in the Gastric cancer group (P < 0.01)." (PMID 38301047, 2024). "DSCC1 was also discovered to enhance malignancy in gastric cancer, namely cell proliferation, both in vitro and in vivo." (PMID 39768811, 2024). "The literature review presented aligns with our findings that DSCC1 and GINS1 are overexpressed in Gastric cancer, and higher expression levels are associated with poor prognosis." (PMID 38301047, 2024). "In summary, DSCC1 and GINS1 are overexpressed in gastric cancer, and higher expression levels are associated with worse prognosis." (PMID 38301047, 2024). "Significant gains of genes ATAD2, DSCC1, FAM91A1, and MYC brought to the enrichment of the Gastric Cancer Network 2 pathway, and ATAD2 is a cancer-associated protein which can also induce the expression of Cyclin D1 and MYC." (PMID 31921654, 2019). "DSCC1 and GINS1 might be the complementary biomarkers of computed tomography for diagnostic grading of gastric cancer." (PMID 38301047, 2024). "The findings of this study reveal that DSCC1 and GINS1 are overexpressed in Gastric cancer, and higher expression levels are associated with worse patient outcomes, suggesting that these two genes may play pivotal roles in Gastric cancer." (PMID 38301047, 2024). "However, complementary markers for gastric cancer, relationship between DSCC1, GINS1 and gastric cancer remain unclear." (PMID 38301047, 2024). "The RT-PCR results showed that, compared to the Control group, the mRNA expression levels of DSCC1 and GINS1 in the Gastric cancer group were significantly increased (P < 0.01)." (PMID 38301047, 2024). "Box plots of core gene expression in Gastric cancer and normal samples demonstrated differential expression of core genes (DSCC1 and GINS1), with higher expression in Gastric cancer samples and lower expression in normal samples." (PMID 38301047, 2024). "These heatmaps indicated higher expression of the core genes (DSCC1 and GINS1) in Gastric cancer samples compared to normal samples." (PMID 38301047, 2024). "DSCC1 and GINS1’s significant roles in gastric cancer will be validated using public datasets." (PMID 38301047, 2024). "Consequently, DSCC1 and GINS1 are likely to play important roles in the development of Gastric cancer." (PMID 38301047, 2024). "WB and RT-PCR results demonstrated high expression of DSCC1 and GINS1 in gastric cancer." (PMID 38301047, 2024). "However, complementary markers of computed tomography for diagnostic grading of gastric cancer are currently unclear, and the relationship between DSCC1 and GINS1 and gastric cancer remains unclear." (PMID 38301047, 2024). "However, no research has yet explored the involvement of DSCC1 in gastric cancer or the significance of molecular systems in this context." (PMID 39309429, 2024). "In addition, we examined whether DSCC1 affects cell growth in cells including a normal colon cell line CCD841, gastric cancer cell lines AGS and SNU620, and embryonic kidney HEK293T cells." (PMID 31762824, 2019). "However, the exact relationship between DSCC1, GINS1, and Gastric cancer is not yet clear." (PMID 38301047, 2024).
colon cancer (4 papers, 2014 to 2024). "A study also demonstrated that when cytoplasmic DSCC1 expression is elevated in the area of a tumor, colon cancer patients’ probability of survival decreases." (PMID 39768811, 2024). "A significant correlation between MSI status in patients with colon cancer and elevated cytosolic DSCC1 levels was observed." (PMID 31762824, 2019). "Yamaguchi et al35 demonstrated that DSCC1 is frequently upregulated in colon cancer cells, and these elevated DSCC1 levels confer chemoresistance to colon cancer cells." (PMID 31762824, 2019). "When the mRNA expression of the CTF18-1-8 module in colon cancer tissues was analyzed by qPCR, DSCC1 mRNA increased more strongly compared with CTF18 or CTF8 mRNA (data not shown)." (PMID 31762824, 2019). "It was found that DSCC1 was overexpressed in tumor tissues from patients with colon cancer and that the survival probability of patients with colon cancer was lower when the expression of cytosolic DSCC1 was higher in tumor regions (P=0.047)." (PMID 31762824, 2019). "The present study verified the overexpression of DSCC1 in tissues from patients with colon cancer, along with clinicopathological findings indicating a lower survival probability in patients exhibiting elevated cytosolic DSCC1 levels." (PMID 31762824, 2019). "The present study examined DSCC1 overexpression in tissues from patients with colon cancer, revealing that the survival probability of patients with elevated cytosolic DSCC1 expression was lower compared with that of patients displaying localized DSCC1 expression in the nucleus." (PMID 31762824, 2019). "The present findings suggested that DSCC1 may be an important component of the CTF18-1-8 module associated with colon cancer progression and a promising therapeutic target for colon cancer treatment." (PMID 31762824, 2019). "DSCC1 protein was expressed strongly in all colon cancer cell lines examined in the present study." (PMID 31762824, 2019). "DSCC1 is identified as a crucial component of the CTF18-RFC module, highly correlated with the growth and metastasis of colon cancer cells." (PMID 38301047, 2024). "It was identified that DSCC1 of the CTF18-1-8 module is important for CRC growth, and the present study also examined whether the binding of CTF18 to DSCC1 is important for colon cancer cell proliferation and invasion." (PMID 31762824, 2019). "The reason for the high cytosolic DSCC1 of patients with colon cancer could not be explained by DSCC1 mutants, but the tumorigenesis mediated by the cytosolic or nuclear localization of DSCC1 appears to be complicated." (PMID 31762824, 2019). "The present results suggested that DSCC1 is the most important component in the CTF18-1-8 module for CTF18-RFC and is highly relevant to the growth and metastasis of colon cancer cells, and, therefore, it may be a potential therapeutic target for colon cancer treatment." (PMID 31762824, 2019).
lung adenocarcinoma (4 papers, 2023 to 2025). A carcinoma that arises from the lung and is characterized by the presence of malignant glandular epithelial cells. "Research indicates that DSCC1 is significantly expressed in lung adenocarcinoma and associated with an unfavorable prognosis." (PMID 39768811, 2024). "Research suggests that abnormal expression of DSCC1 may be linked to the development of certain cancers, as seen in a study related to lung adenocarcinoma." (PMID 38301047, 2024). "DSCC1 siRNA inhibited the progression of EMT in lung adenocarcinoma cells by increasing E-cadherin and decreasing N-cadherin." (PMID 39768811, 2024). "DSCC1 was shown to increase the metastasis of lung adenocarcinoma cells by increasing their capacity for cell division, stemness, and epithelial–mesenchymal transition (EMT)." (PMID 39768811, 2024). "The results showed that DSCC1 was altered in 17% of liver hepatocellular carcinoma samples and 5% of lung adenocarcinoma samples, indicating the role of genetic alterations in the dysregulation of DSCC1." (PMID 39768811, 2024). "In addition, EEF1A2 interacts with HSP90AB1 to promote lung adenocarcinoma metastasis, and DSCC1 interacts with HSP90AB1 to enhance the proliferation and metastasis of lung adenocarcinoma cells." (PMID 41209079, 2025).
colorectal adenocarcinoma (3 papers, 2014 to 2024). The most common type of colorectal carcinoma. "Differential gene expression analysis showed distinct gene expression patterns in GCA compared to colorectal adenocarcinoma, with a number of cancer-related differentially expressed genes, including upregulation of TMEM14A, GOLT1A, DSCC1, and HSD17B8, and downregulation of KCNQ1OT1 and MXRA5." (PMID 34804955, 2021). "As a result, putative copy number changes were found in 7 of 257 colorectal adenocarcinomas (2.7%), suggesting that amplification of DSCC1 does not play a major role in the enhanced DSCC1 expression." (PMID 24465681, 2014).
hepatocellular carcinoma (2 papers, 2023 to 2024). A malignant tumor that arises from hepatocytes. "Furthermore, DSCC1 promotes proliferation and is associated with poor prognosis of hepatocellular carcinoma." (PMID 37742009, 2023). "DSCC1 is also significantly upregulated in hepatocellular carcinoma, where it facilitates tumor cell proliferation." (PMID 39768811, 2024).
breast tumor (1 paper, 2024). "The DSCC1 protein was expressed in the cytoplasm of invasive breast tumor tissues, with no discernible membranous or nuclear staining and with varying degrees of intensity, from absent to high." (PMID 39768811, 2024).
colorectal tumors (1 paper, 2014). "In the data sets, DSCC1 and CDK1 were significantly up-regulated in colorectal tumors compared with normal colonic tissues." (PMID 24465681, 2014). "Although DSCC1 is located at chromosomal region 8q, which is one of the most frequently amplified chromosomal regions in colorectal tumors, copy number gain or amplification was not involved in DSCC1 up-regulation." (PMID 24465681, 2014). "Quantitative PCR and immunohistochemical analyses corroborated that the expression level of DSCC1 is elevated in 60–70% of colorectal tumors compared to their matched noncancerous colonic mucosa." (PMID 24465681, 2014). "We previously performed gene expression profile analysis in CRC, and identified that DNA replication and sister chromatid cohesion 1 (DSCC1, also known as DCC1) was frequently elevated in colorectal tumors compared with non-cancerous colonic mucosa." (PMID 24465681, 2014).
gastric neoplasm (1 paper, 2024). A benign or malignant neoplasm involving the stomach. "The core genes (DSCC1 and GINS1) were found to be associated with gastric neoplasms, gastrointestinal diseases, tumors, gastritis, inflammation, and necrosis." (PMID 38301047, 2024). "CTD analysis revealed associations between DSCC1, GINS1 and gastric tumors, gastrointestinal diseases, tumors, gastritis, inflammation, necrosis." (PMID 38301047, 2024).
lung carcinoma (1 paper, 2023). "Meanwhile, DSCC1 expression negatively correlated with immune cell infiltration in lung cancer, and DSCC1 positively regulated the expression of PD-L1 in LUAD cells." (PMID 37742009, 2023). "The expression level of DSCC1 was negatively correlated with the immune score of lung cancer." (PMID 37742009, 2023). "In addition, the DSCC1 expression was positively correlated with multiple immune inhibitors in lung cancer, such as PD-L1 and programmed death-1 (PD-1)." (PMID 37742009, 2023). "More importantly, the DSCC1 expression was positively correlated with PD-L1 or PD-1 in lung cancer." (PMID 37742009, 2023). "However, the role and mechanism of DSCC1 in the progression of lung cancer still need further investigation." (PMID 37742009, 2023). "Our data suggested that DSCC1 expression was not only positively corelated with PD-L1/PD-1, but also TMB in lung cancer." (PMID 37742009, 2023). "However, the role and mechanism of DSCC1 in lung cancer progression remain unclear." (PMID 37742009, 2023). "Our data indicated that DSCC1 expression was corelated with PD-1/PD-L1 expression, tumor immune infiltration, and TMB in lung cancer." (PMID 37742009, 2023). "Furthermore, DSCC1 expression correlated negatively with immune infiltration levels of multiple immune cell types in lung cancer and the proportions of B cells, CD4 + T cells, CD8 + T cells, and DC cells were lower in the high DSCC1 expression group than in the low DSCC1 expression group." (PMID 37742009, 2023).
lymphoma (1 paper, 2024). A malignant (clonal) proliferation of B- lymphocytes or T- lymphocytes which involves the lymph nodes, bone marrow and/or extranodal sites. "Dscc1 mutants displayed significantly decreased tumour latency (P < 0.0014, log-rank test), with lymphoma being the predominant malignancy, therefore suggesting that DSCC1 can act as a tumour suppressor." (PMID 38355793, 2024).
metastatic tumors (1 paper, 2023). "Meanwhile, DSCC1 was significantly overexpressed in the metastatic tumors compared with LUAD primary tumors." (PMID 37742009, 2023).
neuroblastoma (1 paper, 2012). Neuroblastoma (NB) is the most common solid, extracranial childhood tumor. "We identified six genes (DLGAP5, DSCC1, SMO, SNRPD1, SSBP1, and UBE2C) with a vital role in mitosis and these are promising therapeutic targets for neuroblastoma." (PMID 23251412, 2012).
prostate carcinoma (1 paper, 2023). A carcinoma that arises from epithelial cells of the prostate gland. "DNA Replication and Sister Chromatid Cohesion 1 (DSCC1), the most important molecular to form a chromosome transmission-fidelity protein 18 (CTF18)-DSCC1-CTF8 (CTF18-1-8) module, is highly corelated with the growth and metastasis of colon or prostate cancer cells." (PMID 37742009, 2023).